H3C13 (H3 clustered histone 13)
Description:
Core component of nucleosome. Nucleosomes wrap and compact DNA into chromatin, limiting DNA accessibility to the cellular machineries which require DNA as a template. Histones thereby play a central role in transcription regulation, DNA repair, DNA replication and chromosomal stability. DNA accessibility is regulated via a complex set of post-translational modifications of histones, also called histone code, and nucleosome remodeling.
Synonyms: HIST2H3D
Tractability: Small molecule: a structure with a bound ligand is known. Antibody: its Gene Ontology location is reachable by antibodies, with high confidence. PROTAC: UniProt records ubiquitination sites on it; ubiquitination databases record sites on it.
Gene: Protein-coding gene on chromosome 1 (149,813,225 to 149,813,693, reverse strand). Ensembl gene ENSG00000183598.
Subcellular location: Nucleus; Chromosome
Subcellular location (Human Protein Atlas): Nucleoplasm
Pathways (Reactome):
Gene expression (Transcription): B-WICH complex positively regulates rRNA expression; DNA methylation; ERCC6 (CSB) and EHMT2 (G9a) positively regulate rRNA expression; MLL4 and MLL3 complexes regulate expression of PPARG target genes in adipogenesis and hepatic steatosis; NoRC negatively regulates rRNA expression; PRC2 methylates histones and DNA; RNA Polymerase I Promoter Escape; RNA Polymerase I Promoter Opening; RUNX1 regulates genes involved in megakaryocyte differentiation and platelet function; RUNX1 regulates transcription of genes involved in differentiation of HSCs; Regulation of endogenous retroelements by KRAB-ZFP proteins; Regulation of endogenous retroelements by Piwi-interacting RNAs (piRNAs); Regulation of endogenous retroelements by the Human Silencing Hub (HUSH) complex; SIRT1 negatively regulates rRNA expression; Transcriptional regulation by small RNAs
Chromatin organization: CHD1 and CHD2 subfamily; CHD6, CHD7, CHD8, CHD9 subfamily; ChAHP complex assembly; Chromatin modifying enzymes; HATs acetylate histones; HDACs deacetylate histones; HDMs demethylate histones; Interaction of NuRD complexes with transcription factors; NuRD complex assembly; PKMTs methylate histone lysines; RMTs methylate histone arginines
Disease: Defective pyroptosis; Dengue Virus-Host Interactions; HCMV Early Events; HCMV Late Events
Signal Transduction: Activated PKN1 stimulates transcription of AR (androgen receptor) regulated genes KLK2 and KLK3; Estrogen-dependent gene expression; Formation of the beta-catenin:TCF transactivating complex; Pre-NOTCH Transcription and Translation
Developmental Biology: Activation of anterior HOX genes in hindbrain development during early embryogenesis; Chromatin modifications during the maternal to zygotic transition (MZT); Transcriptional regulation of granulopoiesis
Immune System: FXIIa activates plasma kallikrein-kinin system; Interleukin-7 signaling; Regulation of PD-L1(CD274) transcription
and 8 more pathways
Gene Ontology:
Molecular function: protein binding; nucleosomal DNA binding; structural constituent of chromatin; DNA binding; protein heterodimerization activity
Biological process: nucleosome assembly; chromatin organization; heterochromatin formation
Cellular component: extracellular exosome; nucleoplasm; nucleosome; nucleus; extracellular region; chromosome
Genetic constraint (gnomAD): Loss-of-function variants: 8 observed, 6.97 expected, observed/expected ratio (o/e) 1.15, 90% interval 0.66 to 1.83. That is too few expected variants to judge how well the gene tolerates losing a copy. Missense variants: 173 observed, 186.49 expected, observed/expected ratio (o/e) 0.93, 90% interval 0.82 to 1.05. Synonymous variants: 110 observed, 82.09 expected, observed/expected ratio (o/e) 1.34, 90% interval 1.15 to 1.57.
Homologues: Orthologues: Drosophila melanogaster His3:CG33806 (100% identical), rat H2bc18 (100% identical), tropical clawed frog h3c14 (100% identical), zebrafish si:dkey-261m9.10 (100% identical). Paralogues in human: H3C14 (100% identical), H3C15 (100% identical), H3C1 (99% identical), H3C10 (99% identical), H3C11 (99% identical), H3C12 (99% identical), H3C2 (99% identical), H3C3 (99% identical), H3C4 (99% identical), H3C6 (99% identical), H3C7 (99% identical), H3C8 (99% identical), and 8 more.
Diseases named in the same sentence as H3C13 in open-access papers:
H3C13 is named in the same sentence as 4 diseases in open-access papers, as found by Europe PMC text mining. Sharing a sentence is not in itself a finding about the gene and the disease. The quoted sentences say what the papers report.
Alcoholism (2 papers, 2021 to 2024). "Estrogen signaling pathway was detected and proteins H3C1, H3C13, H3C15 were associated with pathways such as alcoholism, histone modifications, systemic lupus erythematosus." (PMID 33692444, 2021).
cancer (2 papers, 2024 to 2025). A tumor composed of atypical neoplastic, often pleomorphic cells that invade other tissues. "Notably, our identification of H3-5/H3F3C, H3C13/HIST2H3D, JUN, EGR1, NOTCH1, and SQSTM1/P62 as central hub genes unique to the COVID-19 signature links this pro-oncogenic state to a specific molecular target that regulates inflammation, autophagy, and cancer progression." (PMID 41472277, 2025).
H3C13 also shares sentences with these, for which no sentence is quoted: systemic lupus erythematosus (2 papers); cholangiocarcinoma (1).